PLOD3 (procollagen-lysine,2-oxoglutarate 5-dioxygenase 3)
Diseases named in the same sentence as PLOD3 in open-access papers (continued):
Sharing a sentence is not in itself a finding about the gene and the disease.
lung carcinoma (continued). "To further identify the genes essential for lung cancer metastasis, we generated-specific siRNA constructs to stably knockdown human PLOD3 (hPLOD3) mRNA and transfected siPLOD3 into the R-H460 cells, which express PLOD3 more than H460 cells." (PMID 30442941, 2018). "The mechanism underlying the MMP upregulation and promotion of invasiveness in PLOD3-overexpressing lung cancer cells warrants further investigation." (PMID 30442941, 2018). "Herein, PLOD3 was first confirmed to be frequently upregulated in lung cancer patients upon immunohistochemical analysis." (PMID 30442941, 2018). "First, we experimentally confirmed the release of PLOD3 in circulation in animal models, rendering it a potential serum biomarker for lung cancer in humans." (PMID 30442941, 2018). "We first analyzed PLOD3 expression in tumor samples from lung cancer patients to determine the clinical relevance of PLOD3 expression in lung cancer." (PMID 30442941, 2018). "Clinical data also revealed that PLOD3 expression was significantly correlated with the pathological grade of lung cancer." (PMID 30442941, 2018). "In this context, these findings strongly suggest that PLOD3 knockdown effectively suppresses the constitutive activation of STAT3 in lung cancer cells." (PMID 30442941, 2018). "A previous study showed that PLOD3 can be secreted into the circulation in lung cancer." (PMID 40133271, 2025). "In lung cancer cells, PLOD3 knockdown suppresses chemoresistance and radioresistance, which might promote the curative effect with chemotherapy and radiotherapy." (PMID 34576068, 2021). "In addition, PNA-A15 interferes with both cancer and CSC phenotypes through the regulation of PLOD3, which is a potent inducer of lung cancer metastasis via the RAS-MAPK pathway in vivo." (PMID 34059086, 2021). "Further, PLOD3 might represent a prognostic biomarker and a target for reversing cisplatin resistance in lung cancer." (PMID 30770789, 2019). "Therefore, PLOD3 siRNA suppresses radioresistance and chemoresistance by inducing apoptosis and renders PLOD3 as a candidate lung cancer biomarker." (PMID 30770789, 2019). "PLOD3 gene therapy might enhance the efficacy of radiotherapy or chemotherapy in lung cancer patients." (PMID 30770789, 2019). "Our study showed consistent results for lung cancer and suggests that secreted PLOD3 could serve as a potential inducer of lung cancer metastasis or as a prognostic marker." (PMID 30770789, 2019). "Moreover, lung cancer patients with high PLOD3 expression showed poorer prognosis than those with low PLOD3 expression upon radiotherapy, suggesting that PLOD3 promotes tumor growth." (PMID 30770789, 2019). "As the pathway identified herein might represent a major physiological mechanism in lung cancer, it will be crucial to establish the role of the PKCδ-PLOD3-collagen axis in different tissues in future." (PMID 30770789, 2019). "Thus, the present study provided the first evidence that PLOD3 inhibition can induce apoptosis in lung cancer cells, in addition to helping overcome radioresistance or chemoresistance." (PMID 30770789, 2019). "In particular, the role of PLOD3 in promoting lung cancer metastasis has remained unclear." (PMID 30442941, 2018). "Therefore, secreted PLOD3 serves as a potent inducer of lung cancer metastasis and a potential therapeutic target to enhance survival in lung cancer." (PMID 30442941, 2018). "Moreover, PLOD3 upregulation was significantly correlated with lung cancer stage (comparing I–II–III)." (PMID 30442941, 2018). "Although PLOD3 has been assessed in multiple cancers, its regulation in lung cancers is unclear." (PMID 30442941, 2018). "In addition, PLOD3 knockdown is expected to downregulate JAK1; therefore, we consider that the JAK-PLOD3-STAT3 axis plays an important signaling role in PLOD3-induced lung cancer metastasis." (PMID 30442941, 2018).
lung carcinoma (continued). "Procollagen-lysine, 2-oxoglutarate 5-dioxygenase (PLOD3), a membrane-bound homodimeric enzyme, hydroxylates lysyl residues in collagen-like peptides; however, its role in lung cancer is unknown." (PMID 30442941, 2018). "Notably, in 50 of 59 lung cancer patients, PLOD3 was upregulated in lung cancer tissue than in the corresponding normal tissue." (PMID 30442941, 2018). "We suggest that monitoring of serum PLOD3 levels may, in most cases, provide a more sensitive method for early detection of potentially curable cases of lung cancer metastasis." (PMID 30442941, 2018). "Together, these data suggest that PLOD3 promotes metastasis in lung cancer in vitro." (PMID 30442941, 2018). "Further, PLOD3 levels were determined in lung tissue samples from lung cancer patients." (PMID 30442941, 2018). "The mechanistic study clearly revealed that PLOD3 knockdown inhibits STAT3 activation, suggesting that inactivation of STAT3 signaling by PLOD3 may serve as an effective therapeutic approach for lung cancer." (PMID 30442941, 2018). "Furthermore, the results from mechanistic studies, based on the observed selective regulation of lung cancer metastasis upon PLOD3 depletion, identified STAT3 as the binding partner of PLOD3." (PMID 30442941, 2018). "Our data indicate that PLOD3 regulates lung cancer metastasis directly via STAT3 signaling." (PMID 30442941, 2018). "However, the molecular mechanisms underlying the role of PLOD3 in lung cancer cell death have not been fully elucidated, and there are no data regarding the possible role of PLOD3 in lung cancer cell apoptosis." (PMID 30770789, 2019). "PLOD3 and PLOD2 are overexpressed and secreted by cells of lung cancer, glioma, glioblastoma, and pancreatic duct adenocarcinoma." (PMID 33807594, 2021). "However, the physiological role of PLOD3 in lung cancer remains unknown." (PMID 30442941, 2018). "Together, the findings from in vitro and in vivo analyses and from lung cancer patient samples demonstrate the sufficient and necessary roles of PLOD3, MMP-2/9, and uPA in promoting lung cancer metastasis." (PMID 30442941, 2018). "PLOD3 was upregulated in pathological grade III (n = 10) rather than in pathological grades I (n = 24) and II (n = 25) lung cancer." (PMID 30442941, 2018). "PLOD3 and the STAT3 pathway were significantly correlated in the metastatic foci of lung cancer patients; PLOD3–STAT3 levels were highly correlated with a poor prognosis." (PMID 30442941, 2018). "In addition, PLOD3 interacts with STAT3 immunosuppressive signals, which promotes lung cancer metastasis via dysregulated RAS-MAP kinase pathway." (PMID 34646265, 2021). "In conclusion, the present study identified PLOD3 as a novel pro-metastatic factor in lung cancer and as a novel tumor oncogene with an essential role in inducing metastasis, potentially serving as a promising prognostic biomarker for lung cancer." (PMID 30442941, 2018). "Importantly, the present results help elucidate the mechanism underlying PLOD3-mediated regulation of STAT3 function via direct interactions; PLOD3 may induce robust binding of STAT3 to its consensus-binding elements and upregulate target genes, thereby promoting lung cancer metastasis." (PMID 30442941, 2018). "Furthermore, analysis of the publicly available microarray datasets revealed a correlation between PLOD3 and STAT3 mRNA levels in lung cancer patients." (PMID 30442941, 2018). "To determine whether PLOD3 and STAT3 coordinate to promote lung cancer metastasis in patients, we analyzed the potential correlation between PLOD3 and STAT3 expression levels in lung cancer patients." (PMID 30442941, 2018). "However, for lung cancer, the specific mechanism of PLOD3 regulation in cell death has not been elucidated." (PMID 30770789, 2019). "However, the present study reports that activation of the Ras/MAPK signaling pathway is not essential for PLOD3 knockdown-induced invasion of lung cancer cells." (PMID 30442941, 2018).
lung carcinoma (continued). "PLOD3 knockdown could inhibit tumor growth in lung cancer through regulating the PKC-delta signaling pathway, and also in lung cancer, PLOD3 is found to interact with STAT3 immunosuppressive signals, which promotes lung cancer metastasis via dysregulated RAS-MAP kinase pathway." (PMID 34239923, 2021).
gastric cancer (10 papers, 2018 to 2024). A primary or metastatic malignant neoplasm involving the stomach. "PLOD family members (PLOD1, PLOD2, and PLOD3) were shown to be associated with poor prognosis and could act as potential biomarkers or therapeutic targets for both gastric cancer and hepatocellular carcinoma." (PMID 36820030, 2023). "The PLOD family includes PLOD1, PLOD2, and PLOD3, all of which may be linked to various cancers, including gastric cancer, sarcoma, and liver cancer." (PMID 36820030, 2023). "In addition, we sought to examine the role of PLOD3 on mediating Trastuzumab resistance in gastric cancer and its underlying mechanism by investigating the involvement of FoxO3/Survivin pathway." (PMID 35835735, 2022). "Recent studies found that high levels of PLOD1 and PLOD3 were related to short OS in gastric cancer, and high levels of PLOD1 and PLOD2 were related to poor OS in bladder cancer." (PMID 39068670, 2024). "For example, a study found that a set of enzymes PLOD1, PLOD2 and PLOD3 involved in the hydroxylation of lysine and stabilization of collagen by crosslinks, which up-regulated expression in gastric cancer patients." (PMID 35111402, 2022). "In our study, we show that PLOD3 is a key mediator for HER-2 resistance through downregulating FoxO3 therefore promoting survivin pathway in gastric cancer." (PMID 35835735, 2022). "In conclusion, we show that PLOD3 is a key mediator for HER-2 resistance through downregulating the expression of FoxO3 therefore upregulating Survivin pathway in gastric cancer." (PMID 35835735, 2022). "Based on previous studies, we aim to characterize the role of PLOD3, a key enzyme that catalyzes the lysyl hydroxylation of extracellular matrix collagen, in gastric cancer." (PMID 35835735, 2022). "Herein, we analyzed clinical samples of gastric cancer patients and gastric cancer cell lines and identified PLOD3, unveiled that depletion of PLOD3 leads to decreased cell proliferation, tumor growth and Trastuzumab sensitivity in these Trastuzumab resistant GC cell lines." (PMID 35835735, 2022). "Interestingly, we observed FoxO signaling pathway was one of the most significantly downregulated pathways in PLOD3-low subgroup in gastric cancer." (PMID 35835735, 2022). "Therefore, our study identifies a new signaling axis PLOD3-FoxO3- Survivin pathway that may be therapeutically targeted in HER-2 positive gastric cancer." (PMID 35835735, 2022). "PLOD3 decreases trastuzumab sensitivity by repressing FOXO3, resulting in the upregulation of Survivin protein in gastric cancer." (PMID 39068670, 2024). "We know, Procollagen-Lysine,2-Oxoglutarate 5-Dioxygenase 3 (PLOD3), a key gene coding enzymes that catalyze the lysyl hydroxylation of extracellular matrix collagen, plays an important contributor to HER-2 targeting agent Trastuzumab resistance in gastric cancer." (PMID 35835735, 2022).
hepatocellular carcinoma (9 papers, 2018 to 2025). A malignant tumor that arises from hepatocytes. "In the hepatocellular cancer, PLOD3 was identified as one of the early-stage decision markers that were upregulated in the premalignant lesions." (PMID 34585630, 2021). "Similarly, PLOD3 is overexpressed in ovarian cancer, colon adenocarcinoma, and hepatocellular carcinoma, where it facilitates tumor progression." (PMID 41142622, 2025). "PLOD2 was related to HNSCC, hepatitis C, hepatocellular carcinoma, renal cell carcinoma, and CTLA4 inhibitory signaling while PLOD3 was linked to basal cell carcinoma, renal cell carcinoma, ncRNAs involved in WNT signaling in hepatocellular carcinoma, and FRS-mediated FGFR2 signaling." (PMID 36820030, 2023). "In hepatocellular carcinoma, PLOD2 expression correlated with aggressive progression; moreover, PLOD3 was found to be highly expressed in this cancer and may be a promising diagnostic biomarker." (PMID 31446433, 2019).
ovarian carcinoma (9 papers, 2021 to 2025). A malignant neoplasm originating from the surface ovarian epithelium. "For example, in a most recent study on ovarian cancer, specifically higher PLOD3 expression has been associated with poor prognosis although all PLOD enzymes are overexpressed in ovarian cancer tissue and cell lines." (PMID 39530057, 2024). "In the CPTAC dataset, PLOD3 total protein expresses higher in primary cancers than in normal tissues for COAD, KIRC, UCEC, BRCA and LUAD, while the expression in ovarian cancer shows no increased protein expression." (PMID 34576068, 2021).
colorectal cancer (7 papers, 2019 to 2025). A primary or metastatic malignant neoplasm that affects the colon or rectum. "In this context, we demonstrated that PLOD3 downregulation interfered with tumor progression and was significantly associated with advanced colorectal cancer." (PMID 38184566, 2024). "Clinical data also showed that PLOD3 expression levels significantly correlated with the pathological grade of colorectal cancer." (PMID 38184566, 2024). "In conclusion, our research characterized PLOD3 as a new precancerous metastatic factor for colorectal cancer, a novel oncogene with an important role in the induction of metastasis, and possibly had broader application in colorectal cancer." (PMID 38184566, 2024). "The first discovery is that PLOD3 interferes with colorectal cancer tumor progression by affecting the nuclear translocation of NF-κB." (PMID 38184566, 2024). "We identified the potential role of PLOD3 in colorectal cancer through preliminary bioinformatics screening." (PMID 38184566, 2024). "Herein, this study illustrated the biological function and mechanism of the PLOD3 gene to regulate the process of liver metastasis of colorectal cancer." (PMID 38184566, 2024). "This study revealed the essential biological functions of PLOD3 in colon cancer progression and metastasis, suggesting that PLOD3 is a promising therapeutic target for colorectal cancer liver metastasis." (PMID 38184566, 2024). "Nonetheless, the expression pattern and function of PLOD3 in colorectal cancer were still uncertain." (PMID 38184566, 2024). "PLOD2 and PLOD3 were among 54 glycoproteins found to be upregulated in colorectal cancer compared with normal tissue." (PMID 31446433, 2019). "Our study indicated that knockdown of PLOD3 inhibits NF-κB activation, suggesting that inhibition of NF-κB signaling by PLOD3 may be a promising treatment for colorectal cancer." (PMID 38184566, 2024). "In addition, PLOD3 downregulation improved overall survival in colorectal cancer patients, and PLOD3 could be used as a prognostic marker in these patients." (PMID 38184566, 2024). "In addition, PLOD3 might be associated with the “immune desert” phenotype and promote TVA tumorigenesis and colorectal cancer progression." (PMID 38184566, 2024). "In conclusion, enhanced metabolic and mitochondrial reprogramming are typical features of TVA, and PLOD3 might be related to the “immune desert” phenotype and contribute to TVA tumorigenesis and colorectal cancer development." (PMID 34585630, 2021).
glioblastoma (5 papers, 2018 to 2024). The most malignant astrocytic tumor (WHO grade IV). "PLOD3 was closely related to patients' age, glioblastoma grade, IDH mutation, 1p/19q deletion, MGMT methylation, and survival time." (PMID 39431006, 2024). "To analyze the putative pathological role of PLOD3 in glioblastoma, we performed PLOD3 loss-of-function studies." (PMID 29644003, 2018). "Then, PLOD3-silenced glioblastoma cells were constructed to assess its effects on glioblastoma migration and invasion." (PMID 39431006, 2024). "In our study, with the help of various bioinformatics and molecular biology experiments, we found that circ_0003137 regulated glioblastoma EMT via the PTBP1/PLOD3 signaling axis." (PMID 39431006, 2024). "Then, circ_0003137 promotes the EMT progression of glioblastoma cells by targeting the PTBP1/PLOD3 axis, accelerating the malignant progression of glioblastoma." (PMID 39431006, 2024). "According to the signature that included four genes (TMOD2, CACNG2, PLOD3, and TMSB10), glioblastoma patients were divided into high and low risk score groups." (PMID 35788194, 2022). "In brain tumor, PLOD3 was founded play considerable roles in the proliferation and metastasis of glioblastoma." (PMID 33503035, 2021). "In summary, we report here a previously unrecognized pathological role for deregulated PLOD3 in human glioblastoma." (PMID 29644003, 2018). "The Transwell assay showed that PLOD3 downregulation could suppress the migration and invasion of glioblastoma cells." (PMID 39431006, 2024). "Next, circ_0003117 promotes glioblastoma cell EMT by targeting the PTBP1/PLOD3 axis." (PMID 39431006, 2024). "Altogether, the migration and invasion of glioblastoma cells could be facilitated by circ_0003137 via the PTBP1/PLOD3 axis." (PMID 39431006, 2024). "The RIP-PCR assays showed that only PLOD3 could be enriched by PTBP1 in circ_0003137-overexpressed glioblastoma cells." (PMID 39431006, 2024). "Then, circ_0003137 promotes the EMT of glioblastomas by targeting the PTBP1/PLOD3 axis." (PMID 39431006, 2024). "Also, PLOD3 was upregulated in glioblastoma tissues and cell lines." (PMID 39431006, 2024). "Mechanistically, circ_0003137 physically binds to polypyrimidine tract binding protein 1 (PTBP1), enhancing the stability of procollagen-lysine, 2-oxoglutarate 5-dioxygenase 3 (PLOD3) and promoting the EMT of glioblastoma cells." (PMID 39431006, 2024). "In glioblastoma, a study constructed a signature by four m7G-related genes (TMOD2, CACNG2, PLOD3, and TMSB10) and could predict the prognosis of glioblastoma patients." (PMID 36732869, 2023). "The results from 270 or 218 glioblastoma samples from the GSE16011 and GSE13041 datasets revealed that PLOD3 overexpression was correlated with poor survival (p = 1.824e–6, p = 0.0031, respectively) and was eminently increased in the high-risk group (p = 8.84e−68, p = 2.65e−45, respectively)." (PMID 29644003, 2018). "Similarly, circ_0003137 could not change the half-life of PLOD3 in PTBP1-deleted glioblastoma cells." (PMID 39431006, 2024).
breast carcinoma (3 papers, 2021 to 2025). "Using UALCAN in TCGA, we discovered that PLOD1 and PLOD3 were significantly upregulated in breast cancer tissues compared to normal tissues." (PMID 39068670, 2024). "High expression levels of PLOD family genes were associated with worse disease-free survival and distant metastasis-free survival, while high expression levels of PLOD1 and PLOD3 were related to worse overall survival in all breast cancer patients." (PMID 39068670, 2024). "We found PLOD1 and PLOD3 were highly expressed in breast cancer tissues and in all stage subgroups." (PMID 39068670, 2024). "To investigate the correlation between PLOD family genes and prognostic values in breast cancer, we further proved that high expressions of PLOD1 and PLOD3 were markedly related to worse OS, and all PLOD family genes represented worse DFS and DMFS." (PMID 39068670, 2024).
colon adenocarcinoma (3 papers, 2021 to 2025). "To investigate the expression pattern of PLOD3 in colon adenocarcinoma (COAD), we collected mRNA expression data from The Cancer Genome Atlas (TCGA) and protein expression data from Clinical Proteomic Tumor Analysis Consortium (CPTAC)." (PMID 34239923, 2021). "Moreover, in the study of Deng, PLOD3, as a member of the PLODs family, is considered to be related to immune cell infiltration and genomic instability in colon adenocarcinoma, which makes us wonder whether PLOD2 also plays the same role in MSI GC." (PMID 35789544, 2023). "However, the clinical and functional roles of PLOD3 in colon adenocarcinoma (COAD) have not been investigated." (PMID 34239923, 2021).